IGF2 (insulin like growth factor 2)
Diseases named in the same sentence as IGF2 in open-access papers (continued):
Sharing a sentence is not in itself a finding about the gene and the disease.
tumor (continued). "A large form of insulin-like growth factor 2(IGF-2), which is probably an incompletely processed molecule of IGF-2, is derivedfrom the tumor and considered to be a hypoglycemic mechanism." (PMID 25113505, 2014). "It should be added that HIF-1 stimulates also transcription of IGF2 gene, coding for insulin-like growth factor 2 (IGF2), which facilitates survival of tumour cells also in an environment with an diminished oxygen content." (PMID 24153191, 2013). "The oncofetal IGF2 mRNA-binding protein 1 (IGF2BP1) controls the migration and invasiveness of primary as well as tumor-derived cells in vitro." (PMID 23677615, 2013). "Growth factors such as IGF1 and IGF2 drive HIF-1α through MEK1 and MEK2 signaling, that influences tumor glucolytic activity." (PMID 22875335, 2013). "We further study the correlation of IGF-1, IGF-1R, IGF-2, IGF-2R, and IGFBP-3 mRNA expression with ERα and ERβ mRNA expression in tumor, tumor-adjacent and control endometria." (PMID 22720981, 2012). "Five target genes were significantly overexpressed in the tumour samples compared with normal bladder tissue: FOXM1, IGF2, OSF2, and H19, which promote cell proliferation and growth, and SPP1, which is involved in extracellular matrix interactions." (PMID 22361633, 2012). "IGF2 was overexpressed in NMIBC, and particularly in pTa tumours, whereas it was under-expressed in more than half the MIBC samples." (PMID 22361633, 2012). "The mRNA level of IGF-1, IGF-1R, IGF-2, IGF-2R, and IGFBP-3 was significantly higher in tumor and tumor-adjacent endometrium than that in control endometrium (p < 0.05)." (PMID 22720981, 2012). "The tumor endometrium expressed significantly lower levels of IGF-1, IGF-1R, and IGF-2, and significantly higher levels of IGF-2R and IGFBP-3, compared with tumor-adjacent endometrium (p < 0.05)." (PMID 22720981, 2012). "Tumor IGF-1R and IGF-2 mRNA expression were clearly elevated in 48 paired samples as demonstrated in tissues from four representative patients." (PMID 22159423, 2012). "We tested the expression of IGF-1, IGF-1R, IGF-2, IGF-2R, IGFBP-3, ERα and ERβ mRNA on 58 tumor tissue samples and 31 tumor-adjacent endometrial tissue samples from patients with EAC and 42 normal endometrial tissue samples, using RT-PCR." (PMID 22720981, 2012). "The SHH ligand gene and Gli-inducible target genes (FOXM1, IGF2, OSF2, H19, and SPP1) were overexpressed in tumour samples as compared with normal bladder tissue." (PMID 22361633, 2012). "Mouse models of increased Igf2 signalling recapitulate most of the developmental and growth abnormalities found in BWS, but fail to develop adrenal hyperplasia or tumours." (PMID 22952916, 2012). "The antiapoptotic and mitogenic function of IGF2 is mediated by IGF-1R, and the expression of this receptor has been also demonstrated in SS cell lines and tumor specimens bearing SS18-SSX1 and SS18-SSX2 fusion proteins." (PMID 22550415, 2012). "In this way, increased expression of both IGF-2 and IGF-1R leads to a strong mitogenic feed-forward signaling loop within the tumor." (PMID 21253475, 2011). "It is of considerable importance, that c-Myb regulates Igf2, which allows tumor cells to develop an independent autocrine loop thereby integrating EGF and IGF-2 signaling networks." (PMID 21464922, 2011). "The role of IGF-2R in IGF axis appears to serve as a site for IGF-2 clearance, therefore reduces the availability of a potent ligand for IGF-1R, the major gateway for carcinogenesis, tumor growth and proliferation." (PMID 21729319, 2011). "In summary, all these studies indicate that insulin, IGF-1, IGF-2, and their signalingvia the IR and IGF-1R can induce tumor growth." (PMID 23908801, 2011).
tumor (continued). "Nussbaum and colleagues have reported that IGF-2 and its receptor IGF-2R stimulate tumor cell migration in human hepatocarcinogenesis." (PMID 20569443, 2010). "The eight genes displaying variable DNA methylation patterns in a significant number of tumours (ABCB1, BRCA1, CDKN2A, FOXC1, GSTP1, IGF2, PPP2R2B and PTEN) within the discovery cohort were tested for association with survival by a logrank test." (PMID 20338046, 2010). "The imprinted gene IGF2 was hypomethylated in 10 DCIS, 11 invasive and 5 mixed tumours and hypermethylated in 1 DCIS, 3 invasive and 10 mixed tumours." (PMID 20056007, 2010). "In this study, biallelic and monoallelic IGF2 expressions correlated with hypermethylation and normal methylation of CTCF6, respectively, in two tumours with LOI and seven tumours with ROI." (PMID 19034281, 2008). "Combined bisulphite restriction assay showed that 21 and 33 tumours had hypermethylation and normal methylation at CTCF6, indicating LOH or LOI and retention of IGF2 imprinting (ROI), respectively." (PMID 19034281, 2008). "Biallelic and monoallelic IGF2 expressions correlated with hypermethylation and normal methylation of H19 DMR, respectively, in two tumours with LOI and seven tumours with ROI." (PMID 19034281, 2008). "Especially WT1-driven tumors follow a stereotypical pathway of germline WT1 mutations becoming homozygous in renal precursor lesions through 11p LOH, which concomitantly activates imprinted IGF2 expression, with subsequent WNT pathway activation leading to tumor growth." (PMID 40340749, 2025). "Additionally, tumor growth is enhanced by autocrine and paracrine effects of high local IGF-2 concentrations, which stimulates IGF-1R and IR expressed on tumor cells." (PMID 41179270, 2025). "The stimulatory loop formed by GHRH and its receptors can be blocked by GHRH antagonists, which exhibit antitumor functions across various cancer types, by directly inhibiting SV1 signaling or blocking tumor-derived insulin-like growth factor 1 (IGF1) and IGF2." (PMID 40244089, 2025). "While we previously demonstrated that IGF2 contributes to immune evasion, the impact of oHSV-induced IGF1R activation on tumor cell signaling remains unclear." (PMID 41510300, 2025). "Finally, this may be multifactorial secondary to above normal IGF-2 production, reduced hepatic glycogen stores, and gluconeogenesis in the setting of metastases and poor nutrition, and excessive consumption from significant abdominopelvic tumor metabolic burden." (PMID 40727482, 2025). "Targeting pericyte–tumor interactions, including the inhibition of PDGF-BB signaling and IGF2 pathways, could counteract their growth-promoting effects on BM cells." (PMID 39858080, 2025). "Additionally, tumour heterogeneity contributes to the variance in IGF‐2 secretion and metabolic impact, reflecting in the IGF‐2:IGF‐1 ratio." (PMID 38411039, 2024). "Moreover, the downstream products of the HIF-1α signaling cascade include vascular endothelial growth factor (VEGF), erythropoietin (EPO), and insulin-like growth factor 2 (IGF2), involved in tumor-induced angiogenesis." (PMID 38791432, 2024). "Additionally, we observed predominant PD-L1 expression on iCAFs, similar to IGF2 and CXCL12, suggesting the pivotal role of iCAFs in tumor immunosuppression." (PMID 39545420, 2024). "After that, we re-subtypeed tumor cells, and annotated them according to each cell marker gene, and identified six tumor cell subtypes: C0 XIST+ tumor cells, C1 SCGB2A1+ tumor cells, C2 IGF2+ tumor cells, C3 UBE2C+ tumor cells, C4 TFF3+ tumor cells and C5 IGFBP3+ tumor cells." (PMID 39896800, 2024). "CircTMEM45A (has-circ-0066659) acts as a sponge for miR-665, regulating the expression of downstream insulin-like growth factor 2 (IGF2) to promote cell migration in vitro and the occurrence of HCC in vivo, and its expression correlates with tumor size, TNM staging, and vascular invasion." (PMID 39444611, 2024).
tumor (continued). "Overall, IGF2 expression in tumor and non-tumor pediatric liver tissues was regulated both through promoter usage and parental imprinting." (PMID 37932266, 2023). "Additionally, IGF1 and IGF2, which activate PI3K signalling in tumours in an autocrine manner, were also significantly upregulated in MPT tumours compared to IDC." (PMID 36522480, 2023). "Using IGF2 mRNA expression data in tumour tissues, we found an obvious negative correlation with IGF2 methylation (r=-0.24, P<0.001)." (PMID 37213278, 2023). "These infiltrated immune cells and solid tumor cells release tumor-progressing cytokines (IL-6, TNF-α, TGF-β), chemokines (CCL2, CCL5, CCL18, CXCL8, CXCL12), and growth factors (EGF, PGF, IGF-1, IGF-2, PDGF) that promote tumor microenvironment immunosuppressive." (PMID 37371075, 2023). "IGF2 expression on the other hand, was not altered in primary tumor tissue, but decreased in metastatic tumor tissue." (PMID 37248468, 2023). "Furthermore, HOTTIP upregulates insulin-like growth factor-2 (IGF-2), which has a role in tumor progression." (PMID 36770654, 2023). "In a transgenic mouse model with liver‐specific IGF2 overexpression, a 20‐ to 30‐fold increase in circulating IGF2 (relative to wild‐type mice) did not lead to a widespread tumor formation." (PMID 36971212, 2023). "However, tumor cells secrete IGF-2, and tumor-derived IGF-2 is persistent in the tumor microenvironment, keeping this signaling cascade activated." (PMID 35017650, 2022). "Notably, in the invasive tumors caused by ERBB2 and ERBB3, THE insulin-like growth factor 2 (IGF2) and insulin-like growth factor binding protein 5 (IGFBP-5) are highly expressed, and these growth factors are very important for tumor growth." (PMID 35990843, 2022). "A LOI at 11p15.5 (IGF2:TSS LOM) was detected in breast (33%) and colorectal (80%) tumor tissues." (PMID 35804856, 2022). "In addition to expression of the hub genes, we noticed that GPC3 and IGF2 were expressed in 65–75% and AFP in more than 40% of the tumour samples." (PMID 36345011, 2022). "In addition, loss-of-heterozygosity of IGF2R favors the interaction between IGF2 and IGF1R in different tumor types." (PMID 33673232, 2021). "Since blocking IGF1R prevented the rescue phenotype mediated by IGF2 supplementation, we explored whether blocking the IGF1R pathway with AEW541 could enhance the anti-tumor efficacy of isiPI3K in sensitive and resistant cell lines." (PMID 34067117, 2021). "Interestingly, the proteoglycan decorin acts as a tumor suppressor by binding and negatively regulating IGF1, IGF2, insulin, IGF1R and IR-A activity." (PMID 34440844, 2021). "As a consequence, utilizing the off-target IGF1R suppressor ceritinib may pave the way for the remedy of tumor cells driven by IGF1R and IGF2." (PMID 33768092, 2021). "Notably, IGF2BP3 sustained IGF2 and IGF1R mRNA translation in tumor cells but any involvement of the IGF2BP3/IGF2/IGF1R axis in response to BET inhibitors has not been yet established." (PMID 34440844, 2021). "Mice bearing IGF-1- and IGF-2-overexpressing MCF-7L cells had earlier onset of tumorigenesis and increased tumor growth rate compared with mice bearing control MCF-7L cells, which is probably due to increased amino acid synthesis under the regulation of IGF signaling." (PMID 33429867, 2021). "The western blotting showed that significant levels of high molecular weight IGF-2 were accumulated in tumors at the preoperative stage, but not in the serum obtained 3 days after tumor resection." (PMID 33841338, 2021). "In contrast, IGF-1R expression decreases with cancer dedifferentiation, suggesting that the IGF-2/IR-A loop plays a more important role than does the IGF-1/IGF-1R loop in thyroid cells dedifferentiation, the acquisition of a stem-like phenotype, tumor progression, and metastasis." (PMID 33669363, 2021).
tumor (continued). "Moreover, increasing evidence has indicated that LSS mediates tumour metastasis directly by acting on cytokines and their receptors in tumour cells, such as VEGF, IL11, and IGF-2." (PMID 32000836, 2020). "IGF-1R binding with either IGF-1 or IGF-2 will undergo receptor autophosphorylation and cross-linking, and then the signals activate both PI3K/Akt/mTOR and Ras/Raf/MEK/ERK pathways to enhance tumor progression." (PMID 32498447, 2020). "Positive regulation of the sponge molecules increases the expression of miR-615-5p target genes such as IGF2, AKT1/2 and SHMT2, which nullifies the tumor suppressor effect of miR-615-5p and leads to cell proliferation, invasion, migration and inhibition of apoptosis." (PMID 32605009, 2020). "The findings in some of these studies have additionally suggested that ZKSCAN3 could modulate several molecules known to play a key role in tumorigenesis and/or tumor progression, such as cyclin D1/D2, EGF, IGF-2, integrin-β4, MMP2/MMP9, NF-κB, and VEGF." (PMID 32824199, 2020). "Although the concentration of IGF2 in blood circulation is higher than that of IGF1, IGF1 plays a more important role in tumor progression than IGF2 because it is regulated by growth hormones, is not easily degraded, and has 15 times higher affinity with IGF1R." (PMID 32665850, 2020). "Contrary to our expectation, western immunoblot analysis of tumor extracts obtained from his autopsy specimens showed that big IGF-2 had been produced only by the preexisting SFT, not by the peri-renal tumor." (PMID 32993631, 2020). "Because it is not feasible to evaluate IGF2 disorders (a kind of carcinogenic driver) by detecting tumor mutations alone, scRNA-seq of CTC is an excellent tool for detecting non-mutable drug-related gene abnormalities, such as IGF2 overexpression." (PMID 33614479, 2020). "Indeed, CAF-secreted IGF-2 as well as IL-6 and IL-8 produced by CD-10+ GPR-77+ CAFs are promoting cancer stemness and tumor formation in lung cancer." (PMID 33553157, 2020). "qPCR confirmed that the relative cycles of Igf2 and H19 significantly decreased in the tumor compared with controls and non-tumor livers." (PMID 32372053, 2020). "Additionally, expression of only three proteins, namely TGF-α, IGF2, and MMP-2, was significantly elevated in the metastatic CRC group, independently of the other variables (e.g., tumor classification, histological grade, and patient age)." (PMID 31623387, 2019). "Other research, analyzing patient-derived tumor xenografts and response to cetuximab, noted frequent IGF2 upregulation (16%) that was mutually exclusive with IRS2, PIK3CA, PTEN, and INPP4B level alterations, supporting IGF2 as a potential drug target." (PMID 31623387, 2019). "IGF2 mRNA-binding protein 1 (IMP1) is a key regulator of messenger RNA (mRNA) metabolism and transport in organismal development and, in cancer, its mis-regulation is an important component of tumour metastasis." (PMID 30864660, 2019). "In vivo experiments showed that inhibition of miR-483-3p reduced tumor formation, whereas IGF2 knockdown did not induce any differences relative to the control." (PMID 31320614, 2019). "In addition to the IGF2/H19 cluster, possible candidates include those genes from the HOX family and the tumor suppressors." (PMID 31426508, 2019). "Indeed, experimental data suggest that IGFBPs sequester circulating IGF-1 and IGF-2, thus limiting their IGF-IR interaction and exerting a tumor suppressor activity." (PMID 31269742, 2019). "Other signalling pathways significantly deregulated in AFP-high tumours and worthy of further analysis include IGF2–IGFR, mTOR, NOTCH and BAP1." (PMID 31285588, 2019). "IGF2 and IGF1R were highly expressed by three HGNET-BCOR tumor samples and PhKh1 cells." (PMID 31234291, 2019). "They demonstrated that IGF2BP3 increases the IGF-2 protein level without increasing its transcript level, and promotes tumor growth by activating downstream effectors such as PI3K and MAPK." (PMID 30760837, 2019).
tumor (continued). "The results showed that total pro‐MMP‐1 protein expression and its corresponding MMP‐1 activity were higher in MSCs with greater tumor‐tropic potential in comparison with the poorly migrating MSCs, suggesting possible crosstalk between MMP‐1 and IGF‐2 signaling." (PMID 29321953, 2018). "In conclusion, our study provided robust evidence that miR-486-5p acted as a tumor-suppressor gene to inhibit CRC cells' proliferation and migration through regulating PLAGL2/IGF2/β-catenin expression and served as a novel prognostic and diagnostic biomarker of CRC." (PMID 30305607, 2018). "Taken together, these results demonstrated that MMP‐1 secreted by MSCs could efficiently cleave the IGF‐2/IGFBP2 complex, facilitating the migration of MSCs toward tumor cells via the IGF‐2/IGF‐1R signaling axis." (PMID 29321953, 2018). "Unlike tumor epithelial IGF2 expression, the malignant stromal IGF2 expression was not prognostic of disease progression or survival." (PMID 29455465, 2018). "For example, IGF2BP1 expression might upregulate RGS4 mRNA and inhibit tumor cell proliferation and invasion, while downregulate GDF15, IGF2, and PTG2 mRNAs and lead to suppression of tumor cell proliferation and invasion." (PMID 29954406, 2018). "Our data demonstrated that MMP‐1 secreted by highly tumor‐tropic MSCs could act as IGFBP2 proteinase, resulting in cleavage of the IGF‐2/IGFBP2 complex followed by the extracellular release of free IGF‐2." (PMID 29321953, 2018). "Furthermore, highly tumor‐tropic MSCs expressed higher levels of MMP‐1 and insulin‐like growth factor (IGF)‐2 than poorly migrating MSCs." (PMID 29321953, 2018). "In addition, it has been proposed that the dysregulation of DNA methylation of RPL30, ALDOB, IGF2, and TIMP1 is sufficient to trigger tumor progression." (PMID 30344796, 2018). "These novel findings suggest that tumor epithelial IGF2 expression is not only a prognostic biomarker in UCS, but also that IGF2 expression differences may contribute to the racial disparity in disease outcome in patients with UCS." (PMID 29455465, 2018). "While the IGF pathway as a system has recently been shown to be significantly associated with PCa mortality, there was no specific correlation between elevated IGF2 and tumor stage, Gleason score, or PSA levels." (PMID 29239100, 2018). "Strong correlation between IGF2 and AFP levels and tumor diameter was found." (PMID 29702590, 2018). "IGF2 expression (either high or low) was not directly correlated with tumor stage, Gleason grade, or PSA level." (PMID 29239100, 2018). "Among the rather limited set of stromal-derived secreted factors in our detergent-extracted matrisomes, IGF2 and Wnt5A (a non-canonical Wnt ligand) were present in the matrix of both tumour-derived fibroblast preparations." (PMID 28102238, 2017). "To compare the CIMP classifications derived from our clustering analysis to those derived from the Weisenberger panel of genes, we analysed the methylation status of our tumour samples using MethyLight at each gene from this panel (CACNA1G, NEUROG1, SOCS1, IGF2, RUNX3)." (PMID 28351398, 2017). "An H19 knockout mouse model (H19Δ3) showed increased tumor development and tumor cell proliferation after treatment with the carcinogen diethylnitrosamine (DEN) independent of the reciprocally imprinted insulin-like growth factor 2 (IGF2)." (PMID 31225433, 2017). "Our study demonstrated a novel paradigm of ESCC progression that involves the orchestration of cancer and non-cancer cells in the tumour micro- and macroenvironments by the Id1/IGF2/VEGF/VEGFR1 cascade." (PMID 28186102, 2017). "However, the IGF-2/IR-A loop appears to be more important than the IGF-1/IGF-1R loop in thyroid cells with dedifferentiated and stem-like phenotype involved in tumor progression and metastasis." (PMID 29184536, 2017).